CRP (C-reactive protein)
Diseases named in the same sentence as CRP in open-access papers (continued):
Sharing a sentence is not in itself a finding about the gene and the disease.
COVID-19 (continued). "Also, in addition to thrombocytopenia, inadequate oxygen saturation values, altered liver function, elevated C-reactive protein (CRP) and lactate dehydrogenase (LDH) levels, lymphopenia, altered neutrophil-lymphocyte ratio (NLR) and D-dimer levels were correlated with the worsening of COVID-19." (PMID 39274209, 2024). "Also, COVID-19 patients with AKI show higher levels of CRP than those without AKI." (PMID 38975470, 2024). "It was clearly demonstrated that treating moderate COVID-19 cases with IFN-α2b could accelerate viral clearance while maintaining adequate levels of circulating pro-inflammatory cytokines such as IL-6 and CRP (C-reactive protein) to strengthen the patients’ immunity against the disease." (PMID 37108513, 2023). "Severe manifestations of COVID-19 may be partly accounted for by an autoimmune reaction mediated by a dysregulated network of circulating proinflammatory cytokines and inflammatory markers, including IL-1β, IL-6, IL-2, IL-8, IL-17, TNF-α, C-reactive protein, D-dimer, and antibodies." (PMID 37712090, 2023). "Cohort A consisted of patients with COVID-19 with a negative CT scan for pulmonary thrombosis and elevated thromboinflammatory markers (D-dimer > 10,000 ng/mL or 5,000 < D-dimer < 10,000 ng/mL and one of: C-reactive Protein > 100 mg/dL, IL-6 > 6 pg/mL, or ferritin > 900 ng/L)." (PMID 36873865, 2023). "Our results show that CRP levels are significantly elevated in SARS-CoV-2-infected individuals, which is consistent with previous research, and it may indicate COVID-19 changes earlier than chest CT—CRP was significantly elevated before CT findings in severe COVID-19 patients." (PMID 37496884, 2023). "The absence of CRP mediation between BMI and hospitalization outcome could be explained by the advanced age of the cohort, where BMI may fail to represent visceral adiposity, an important correlate with respiratory failure in COVID-19 patients." (PMID 38003780, 2023). "In addition, CRP serum level was associated with PCS in men but not in women, probably because of a higher biological response to pro-inflammatory cytokines in men than in women during COVID-19." (PMID 36836568, 2023). "We confirmed this CRP data, and, since we focused on the blood biochemical parameters, we did show that TnT, FBG, glycemia, CPR, LDH, albumin, D-dimer, MGB, and ferritin for both men and women might represent useful indicators of severe morbidity and mortality for Omicron COVID-19." (PMID 37110348, 2023). "Thus, we were able to identify that the CRP serum levels, among all investigated biomarkers, best discriminate between severe and non-severe subjects, while suPAR showed significant higher values in Delta-infections, and LDH proved to be an excellent predictor for mortality in COVID-19." (PMID 37388734, 2023). "In addition, Guyi Wang and colleagues conclude that an optimal threshold value of 26.9 mg/L of CRP could be a valuable marker to anticipate the possibility of aggravation of adult patients with non-severe COVID-19." (PMID 37662725, 2023). "Spearman’s analysis in patients with severe COVID-19 and smokers does not show a correlation between variables analyzed with genotype GG (rs16969968); however, the GA + AA group had a high positive correlation (p < 0.001, rho = 0.753) between fibrinogen and C-reactive protein." (PMID 37372959, 2023). "Moreover, levels of CRP, IL-6, IL-8, IL-10, tumor necrosis factor (TNF)-α and IL-2R showed a positive correlation with high-sensitivity cardiac troponin I, consistent with the contribution of the inflammatory response to cardiac injury present in COVID-19 patients." (PMID 37168848, 2023). "C-reactive protein is a nonspecific acute-phase protein produced in the liver that is upregulated by inflammatory processes and may be an indicator of systemic inflammation and the severity of COVID-19." (PMID 37568161, 2023).
COVID-19 (continued). "Based on this updated meta-analysis included 9 RCTs with 718 patients, we found that melatonin may not offer additional benefits to patients with COVID-19 in general, with regards to mortality, recovery of the symptoms, and the reduction in inflammatory markers such as CRP, ESR, and NLR." (PMID 37181363, 2023). "Additionally, patients with COVID-19 had significantly higher levels of systolic blood pressure (SBP) (p = 0.020), diastolic blood pressure (DBP) (p = 0.001), FPG (p < 0.001), urea (p = 0.003), ferritin (p < 0.001), CRP (p < 0.001), and MDA (p = 0.038) than healthy controls." (PMID 35746958, 2022). "However, this study did not report on CRP, the widely used clinical COVID-19 marker." (PMID 36181766, 2022). "Importantly, the prognosis from COVID-19 patients with severe illness is linked with the lower concentrations of several inflammatory cytokines including ICAM, TNF-α, and CRP, suggesting that ICAM might display an important role in the pathogenesis of COVID-19." (PMID 36290585, 2022). "This could be an important finding which differed from other studies considering a meta-analysis study conducted by Yassin and his colleagues which demonstrated that CRP level was not different between stroke patients with COVID-19 and without COVID-19 infection." (PMID 35991587, 2022). "The COVID-19 positive cohort did, however, present with statistically significant increases in bilateral chest X-ray changes (p-value 0.0009) and levels of eosinophils (p-value 0.002), in agreement with literature observations, but not for C-reactive protein (CRP, p-value 0.80)." (PMID 36137157, 2022). "However, the Kaplan–Meier survival curves and Cox proportional hazard model analysis showed that CRP could not be used as an independent factor to predict the severity of COVID-19." (PMID 35453906, 2022). "Results indicate the feasibility of predicting the forthcoming deterioration of non-severe COVID-19 patients by eight routinely collected blood parameters, including neutrophil, lymphocyte, monocyte, and platelets counts, neutrophil-to-lymphocyte ratio, CRP, LDH, and D-dimer." (PMID 36357439, 2022). "Thus, as CRP is consistently elevated, it might not have a predictive value for bacterial infections in COVID-19." (PMID 36301096, 2022). "As compared to physiological CRP concentrations that range between 0.8 and 3.0 mg/L, CRP levels in COVID-19 patients were strongly increased, with the highest levels being expectedly recorded at the beginning of hospitalization (except for the two patients who did not survive COVID-19)." (PMID 35495660, 2022). "Our findings reveal that CRP, SAA, VCAM-1, CXCL10, CCL22 and IL-10 levels are promising biomarkers for COVID-19 disease severity, suggesting that plasma inflammatory mediators could be used as warning indicators of COVID-19 severity, aid in COVID-19 prognosis and treatment." (PMID 35958594, 2022). "In addition to IL-6, other inflammatory protein such as CRP, serum ferritin and coagulation index, and D-dimer were elevated in patients with COVID-19 and diabetes compared to those without diabetes, indicating that patients with comorbidities are more prone to an inflammatory response." (PMID 35162870, 2022). "Notably, for PCSK9 inhibitors, another class of lipid-lowering drugs that significantly decreases LDL-C but not inflammatory markers like CRP, evidence is lacked so far regarding their possible benefits on COVID-19 outcomes, while deeper investigation is needed." (PMID 35811982, 2022). "Our work showed a short course of MP therapy could not rapidly improve the immune disorders among severe COVID-19 patients or clinical outcomes, also confirmed “core signature” cytokines, as severity biomarkers similar to CRP, could be applied to evaluate clinical treatment effect." (PMID 35350784, 2022).
COVID-19 (continued). "Moreover, the performance of the combination of the ESR, NEU, CRP, Albumin, RBC, Chlorine, and RDW features in detecting infected patients being higher than their individual performance indicates a high level of confidential information about COVID-19 among these blood features." (PMID 35808317, 2022). "A persistent inflammatory state and immune activation, characterized by increased blood levels of the inflammatory cytokines–TNFα, IL-6, IL-1 and CRP, although not specific to COVID-19, may induce apoptosis with secondary endothelial dysfunction and may increase intrahepatic clot development risk." (PMID 36556915, 2022). "In addition, an elevated CRP may not be attributable to COVID-19 alone and may represent concomitant pathology such as secondary bacterial pneumonia." (PMID 33683344, 2021). "However, another study which included 25 confirmed COVID-19 patients who were admitted to ICU showed that circulating levels of IL-2, interleukin-4 (IL-4), tumor necrosis factor-α (TNF-α), interferon (IFN-γ) and CRP were not directly correlated with symptom severity of COVID-19." (PMID 34282057, 2021). "This suggests that neutrophils might be involved in aggravating inflammation and is consistent with studies that show an increase in nonspecific acute-phase CRP and D-dimer inflammatory biomarkers in COVID-19, particularly in patients who subsequently have poor outcomes." (PMID 33651717, 2021). "Thus, COVID-19 patients who died had a high level of solTNFR1, with a negative correlation with CRP; these data suggested that other pro-inflammatory mechanisms (independent of the classical CRP) could be activated in severe COVID-19 patients." (PMID 34445140, 2021). "We included a homogenized population of patients with severe COVID-19 and administered tocilizumab at the time of clinical and physiological deterioration, as assessed by PaO2/FiO2 < 200 irrespective of levels of non-specific inflammatory markers including CRP and ferritin." (PMID 34937570, 2021). "However, symptomatic COVID-19 patients had significantly higher iron concentration and lower CRP level in comparison to those without GI problems (22.9 (21.3–23.4) vs. 16.1 (11.7–19.7) μmol/L; p < 0.001 and 1.2 (0.77–6.61) vs. 5.6 (2.2–21.3) mg/L; p = 0.03; respectively)." (PMID 34680053, 2021). "Therefore, it seems that CRP could not be a reliable marker for the severity of the disease in COVID-19 infant patients." (PMID 34118894, 2021). "Here we systemically analyzed the clinical characteristics of pregnant and non-pregnant female COVID-19 patients who were hospitalized during the same period and found that pregnant patients developed marked lymphopenia and higher inflammation evident by higher C-reactive protein and IL-6." (PMID 34326311, 2021). "In addition, it has been reported that IL-6, high-density lipoprotein (HDL) cholesterol, creatinine, C-reactive protein, high-sensitivity cardiac troponin I (hs-cTnI), D-dimer levels and prothrombin time were significantly higher in the severe COVID-19 CVD group than those in the non-severe one." (PMID 34834033, 2021). "In the COVID-19, but not in the control cohort (for available parameters), ePWV weakly correlated with laboratory markers of disease severity including C-reactive protein (CRP), white blood cells (WBC), decreased lymphocyte count and high-sensitive Troponin-T (hsTnT)." (PMID 34642385, 2021). "Therefore, our findings suggest that the LDH, ALB and CRP are of practical value in identifying patients with COVID-19 whose nucleic acid could turn negative during the quarantine period (14 days)." (PMID 33663273, 2021). "However, owing to the COVID-19 pandemic, mother's history of URI in the past three weeks, persistent fever, poor general conditions, leucopenia, lymphopenia, thrombocytopenia, and elevated CRP, COVID-19 PCR testing was requested, which was found to be positive." (PMID 34961833, 2021).
COVID-19 (continued). "Besides the higher CRP and lower lymphocyte count levels, GDF-15 concentrations were higher in patients with moderate to severe COVID-19 during acute infection as compared to those with mild COVID-19 and controls, and GDF-15 concentrations remained elevated at follow-up." (PMID 34333238, 2021). "Therefore, elevated CRP could provide additional laboratory investigational data for COVID-19 patients, particularly in the absence of specific COVID-19 testing." (PMID 33187475, 2020). "Furthermore, the principal laboratory derangements seen in COVID-19 patients includes anemia, lymphopenia, elevated ferritin, elevated liver enzymes AST (aspartate transaminase) and ALT (alanine aminotransferase), elevated CRP (c-reactive protein), elevated D-dimer, and thrombocytopenia." (PMID 32708430, 2020). "Among the survivors versus non-survivors of COVID-19, there were significant differences in total leukocyte count (p<0.001), neutrophil count, (p<0.001), lymphocyte count (p<0.001), urea (p<0.001), serum bicarbonate (p=0.001), CRP levels (p<0.001), LDH (p=0.013), and D-dimer (p<0.001) at admission." (PMID 32913691, 2020). "Similarly, IFN-α2b treatment of COVID-19 patients as a single agent or in combination with arbidol significantly reduced the duration of SARS-CoV-2 in the upper respiratory tract and reduced the duration of IL-6 and C-Reactive Protein (CRP) inflammatory markers in the blood." (PMID 32882823, 2020). "Production of IL-6 by monocyte, dendritic cells, and macrophage in patients with severe COVID-19 leads to systematic pro-inflammatory cytokines and CRP production and in the absence of anti-inflammatory cytokines may lead to a high-grade inflammation and cytokine storm." (PMID 32876941, 2020). "The mild COVID-19 group and the regular CAP group exhibited no significant changes in inflammatory markers, including CRP and ESR." (PMID 41487633, 2025). "Initial blood tests showed elevated c-reactive protein (CRP) (54 mg/L) but no serial elevation in serum troponin levels, suggesting suspected pericarditis secondary to the COVID-19 vaccination." (PMID 40046975, 2025). "Among severe COVID-19 patients, 26 reacted to ANA, 16 to VDRL, 2 had elevated RF, 12 had increased PCT, and 11 had high CRP, whereas the control group showed no reactive results." (PMID 41259457, 2025). "However, a comparison between COVID-19 patients with and without T2D revealed notable disparities in hospital stay duration (13 days vs. 9.0 days), mortality rates (13% vs. 0%), inflammatory levels (C-reactive protein: 46 ng/ml vs. 8 ng/ml), and HbA1c (8.05 vs 5.70 %)." (PMID 40471558, 2025). "In the COVID-19 cohort, correlations of LPC species with CRP, procalcitonin, and IL-6 were not significant (p > 0.05 for all)." (PMID 41007672, 2025). "Laboratory findings showed the following results: white blood cell (WBC), 5.8 * 109/L; CRP, 103.9 mg/L; platelet (PLT), 184 * 109/L; alanine transaminase (ALT), 131 U/L; and COVID-19 nucleic acid test, negative." (PMID 41552719, 2025). "The admission C-reactive protein (CRP) profiles were compared between the severe and nonsevere COVID-19 patients." (PMID 38905361, 2024). "In contrast, in COVID-19 patients, ACBP plasma concentrations correlated with the neutrophil/lymphocyte ratio, CRP and IL-6 but not IL-1β and IL-8." (PMID 39835130, 2024). "By 21–24 weeks after COVID-19 onset, participants with ongoing PASC at 24 weeks after COVID-19 onset had higher concentrations of CRP in multivariable analyses compared to participants without PASC." (PMID 39008486, 2024). "The time from the onset of COVID-19 symptoms to clinical cure ranges from 8 to 53 days, with large inter-individual variability, and IGFBP-2, CRP, procalcitonin, and IL-6 were not related to the time of blood collection in our cohort." (PMID 38255230, 2024). "Key biomarkers (CRP, ferritin, NLR, and albumin) exhibited distinct distributions across COVID-19 positive and negative cases." (PMID 39767161, 2024).
COVID-19 (continued). "Our study shows good prognostic performance of CRP and IL6 for 28-day hospitalization in patients with mild-to-moderate COVID-19, in the absence of clinical criteria for admission upon enrolment." (PMID 39664394, 2024). "Regarding other laboratory parameters, consistent associations have been documented between increased levels of C-reactive protein, ferritin, INR, and NLR in patients with negative COVID-19 outcomes, such as severity or death." (PMID 38601541, 2024). "A recent study indicated that COVID-19 patients treated in the ICU exhibited higher levels of LDH and CRP than patients who did not receive ICU treatment, suggesting that CRP and LDH levels are primarily associated with a poor prognosis." (PMID 38957300, 2024). "Our objective was to compare the kinetics of three conventional markers routinely used in everyday practice (CRP, PCT, and IL-6) and two non-conventional markers (NLR and PLR) in critically ill COVID-19 patients requiring life-maintaining therapy." (PMID 39336857, 2024). "However, neither CRP nor PCT could predict poor outcomes in diabetic patients with COVID-19." (PMID 38455656, 2024). "C-reactive protein (CRP), alpha-1-acid glycoproteins (A1AG1 and A1AG2), and CXCL7 were all found to be considerably higher in critically ill patients than in non-critical COVID-19 patients, whereas CCD34, C4BPA, and GELS were found to be significantly lower." (PMID 38291452, 2024). "Comparing COVID-19 without acute diabetic complications (ADC), patients with DKA or HHS showed elevated levels of c-reactive protein (CRP, P=0.0312) and procalcitonin (PCT, P=0.0270)." (PMID 38455656, 2024). "Similarly, our data indicated that hypertension APs not only had higher WBCs, neutrophils, basophils, IL-6, and CRP levels but also had lower virus-specific IgM levels than non-hypertension APs, which further immunologically confirms that hypertension had adverse effects on COVID-19 APs." (PMID 38666774, 2024). "Patients with severe COVID-19 and vancomycin-resistant enterococci (VRE) bacteremia had elevated calprotectin levels, but their C-reactive protein and procalcitonin levels were not increased." (PMID 39273246, 2024). "C-reactive protein (CRP) and procalcitonin levels, which are commonly used as inflammation markers, did not increase with lower LDL-cholesterol concentrations in COVID-19 cohorts." (PMID 39408818, 2024). "In candidemia patients without COVID-19; MV, hypotension, CCI, SIRS ≥2, and higher aPTT, procalcitonin, CRP, and lower LCR were found in the non-survivors than survivors." (PMID 38545189, 2024). "To determine whether CRP can impact the prognosis of COVID-19 in conjunction with the expression of two specific genes, we separated the study participants into two groups - one with positive CRP levels and one with negative CRP levels, based on the reference laboratory." (PMID 38741892, 2024). "Collectively, our study revealed that COVID-19-affected T2DM patients exhibited higher levels of several inflammatory mediators, including CRP, IL-6, and TNF-α in comparison to COVID-19 non-DM patients." (PMID 38675414, 2024). "In candidemia patients with COVID-19; MV, hypotension, and higher procalcitonin, lactate, CRP, NLR, urea, and lower lymphocyte-to-C-reactive protein ratio (LCR) were found in the non-survivors than survivors." (PMID 38545189, 2024). "Available data provide evidence for the differentiation of severe and non-severe cases of COVID-19 based on these biomarkers, including lymphocyte count, lactate dehydrogenase (LDH) and C-reactive protein (CRP)." (PMID 39086948, 2024). "Our study presents compelling evidence of distinct CRP and PCT kinetics in severe COVID-19 patients with and without ICU-acquired infections." (PMID 37834754, 2023). "Comparing the AHT-control cohort with the COVID-19 + AHT cohort, the acute phase protein CRP showed an increase, which is not surprising, as well as the NMR-based inflammatory parameter Glyc/SPC." (PMID 37845506, 2023).